TMEM198B (transmembrane protein 198B (pseudogene))
Gene: Transcribed unitary pseudogene on chromosome 12 (55,832,159 to 55,834,988, forward strand). Ensembl gene ENSG00000182796.
Diseases named in the same sentence as TMEM198B in open-access papers:
TMEM198B is named in the same sentence as 2 diseases in open-access papers, as found by Europe PMC text mining. Sharing a sentence is not in itself a finding about the gene and the disease. The quoted sentences say what the papers report.
glioma (2 papers, 2023 to 2024). A benign or malignant brain and spinal cord tumor that arises from glial cells (astrocytes, oligodendrocytes, ependymal cells). "TMEM198B is highly expressed in glioma tissues and cell lines and mediates trimethylation on H3K4me3 by binding to the SET structural domain of SETD1B, thereby promoting the expression of PLAGL2." (PMID 37088950, 2023). "Furthermore, the pseudogene Transmembrane Protein 198B (TMEM198B) is highly expressed in glioma tissues and cell lines and influences glioma progression by regulating lipid metabolic reprogramming." (PMID 38961907, 2024). "Moreover, TMEM198B is enriched in glioma‐derived exosomes (GDEs) and can be delivered to macrophages and enhance lipid accumulation and fatty acid oxidation (FAO), further inducing macrophages to polarize toward M2, thereby promoting immune escape of glioma cells." (PMID 37088950, 2023).
TMEM198B also shares sentences with these, for which no sentence is quoted: lung carcinoma (1 paper).